MIR664A (microRNA 664a)
Synonyms: hsa-mir-664; MIR664; MIRN664; hsa-mir-664a; mir-664a
Gene: MicroRNA gene on chromosome 1 (220,200,538 to 220,200,619, reverse strand). Ensembl gene ENSG00000281696.
Gene Ontology:
Biological process: RNA processing
Cellular component: nucleolus
Homologues: Orthologues: chimpanzee ptr-mir-664a (100% identical).
Diseases named in the same sentence as MIR664A in open-access papers:
MIR664A is named in the same sentence as 2 diseases in open-access papers, as found by Europe PMC text mining. Sharing a sentence is not in itself a finding about the gene and the disease.
MIR664A shares sentences with these, for which no sentence is quoted: cancer (1 paper); melanoma (1).